INS (insulin)
Diseases named in the same sentence as INS in open-access papers (continued):
Sharing a sentence is not in itself a finding about the gene and the disease.
infection (continued). "The use of perioperative continuous intravenous insulin infusion in diabetic patients undergoing open heart surgical procedures appears to significantly reduce the incidence of major infections." (PMID 20137090, 2010). "This value increased to as high as 19.0 integration events (in average) per cell in the presence of 200 μM INS and to 30.0 integration events (in average) per cell following infection of the INS-treated HeLa P4 cells with ΔRev virus." (PMID 20678206, 2010). "The decreased insulin levels observed during infection in the mouse model of T. cruzi infection are consistent with a physiological response to the very low glucose levels." (PMID 19644556, 2009). "As expected, adenoviral UCP2 infection significantly reduced insulin release by INS-1E cells (nearly 40% compared to infection with control adenovirus)." (PMID 19065272, 2008). "Collectively, the expression profile and DAF-16 localization data indicate that PA14 infection induces the expression of ins-7 to activate insulin signaling that leads to inhibition of DAF-16 and downregulation of immune gene expression." (PMID 18927620, 2008). "Infection with adenovirus compromises vital functions of the host cell leading to the activation of protein kinases central to insulin signalling, such as protein kinase B/Akt." (PMID 17309805, 2007). "This study investigated sonic hedgehog (Shh) signalling in gastric metaplasia in the insulin-gastrin (InsGas) hypergastrinaemic mouse +/− Helicobacter felis (H. felis) infection." (PMID 17505514, 2007). "Rayfield and associates studied the effect of acute endotoxemia on volunteers and showed that during the febrile phase of an infection insulin increases to three times basal levels (35 ± 5 μU/ml) and, paradoxically, glucagon increases to five times normal." (PMID 16111485, 2005). "The effect of insulin on lymphocytes becomes significant when seen as part of the profile of events when a body is challenged by infection." (PMID 16111485, 2005). "aeruginosa can sense and respond to mammalian hormones (insulin), which can modulate microbial virulence through diverse mechanisms, providing new insights that may be relevant to infection dynamics." (PMID 41754840, 2026). "In a metabolically stressed state (e.g., from infection, dehydration), insulin secretion may be suppressed, further tipping the balance toward ketogenesis." (PMID 41509085, 2026). "Additionally, factors such as carbohydrate amount and type, physical activity before or after meals, premeal glucose levels and other influences like stress, infection and insulin dose were considered important for maintaining postprandial glucose control." (PMID 41320210, 2025). "Other important factors were inadequate insulin therapy and infection." (PMID 40940823, 2025). "In this study, the infection rate in the intravenous group was 10%, and infection-related inflammatory factors (such as IL-6) could interfere with insulin signaling pathways, exacerbating blood glucose fluctuations." (PMID 40585912, 2025). "Additionally, frequent infections precipitate an increase in cortisol and catecholamines, further antagonizing insulin action." (PMID 40842499, 2025). "The most common precipitating factors were missed insulin doses and infections." (PMID 40755641, 2025). "HCV infection increases the risk of pre‐DM and DM during the initiation of the insulin signaling pathway, comparing individuals with and without infection." (PMID 40539474, 2025). "Compromised insulin signaling early in infection (implied by its later upregulation) could lead to reduced nutrient availability for resident cells and stored sperm, potentially affecting sperm viability and fertility." (PMID 41584795, 2025). "In ICI-DM, abrupt glycemic fluctuations and corticosteroid use may heighten infection risk, underscoring the need for strict glucose monitoring, early insulin initiation, and close infection surveillance." (PMID 41373773, 2025).
infection (continued). "Innate immune signaling acts cell-autonomously to disrupt insulin signaling in the fat body, yet infection and Toll signaling suppress Dilp6 production, likely via Toll pathway transcription factors that may predominate over Foxo to regulate Dilp6." (PMID 41091757, 2025). "The disruption of insulin signaling, combined with proinflammatory and oxidative effects, supports the hypothesis that Mpro could play a role in the development of post-infection glucose dysregulation." (PMID 40843809, 2025). "Moreover, a Jordanian study has found that, in patients with recurrent DKA, 41% of cases were due to missed insulin doses, while 38% were due to acute illness (infection)." (PMID 41375809, 2025). "We next tested if ingested insulin reduced WNV-NY99 infection in adult D. melanogaster." (PMID 39664493, 2024). "In summary, immune cells inside skeletal muscle directly modify the metabolism of myocytes during infection, the purpose of which is to regulate systemic levels of metabolites such as glucose, amino acids, insulin and lactate, which help the immune system better fight infection." (PMID 39107476, 2024). "However, the promoting effects of insulin on the three kinds of cells were weakened after the cells were cocultured with P. gingivalis at a multiplicity of infection (MOI) of 100 (P < 0.05)." (PMID 39085196, 2024). "To examine, insulin was utilized during the infection course." (PMID 38459021, 2024). "Additionally, IP insulin delivery is hampered by several challenges, such as occlusion of the insulin delivery line, which has been reported in several trials of IP insulin delivery and infection at the site of the abdominal port." (PMID 37715091, 2024). "Interestingly, among the few immune-related genes whose expression was increased in the resistant family after infection, an intriguing representation of genes involved in insulin and insulin-like growth factor (IGF) signalling was identified." (PMID 39712009, 2024). "KEGG analysis indicated that these genes could be predominately enriched in pathways related to immune response or infection, and pathways of action cytoskeleton regulation and insulin signaling were also enriched." (PMID 39408874, 2024). "The infection may worsen damage to pancreatic cells, aggravating insufficient insulin secretion and leading to abnormal hormone secretion in mucosal inflammation." (PMID 39054452, 2024). "FOXO is a known regulator of insulin signaling; therefore, we used Thor levels as a read out to see whether insulin signaling in muscles is altered upon infection." (PMID 38566182, 2024). "Moreover, an acute decrease in insulin levels impairs CD8+ T-cell responses to infection, whereas the injection of basal insulin increases the antiviral potential of these cells." (PMID 39722811, 2024). "Hypothetically, infection with the SARS-CoV-2 virus may affect the progression of T1D, inducing a more rapid loss of endogenous insulin production through ß-cell apoptosis, but prospective longitudinal studies are necessary to test this hypothesis." (PMID 39123199, 2024). "Among these subjects, about 80% percent had to increase their insulin dosage by a few units, one subject had to be initiated on insulin in a context of infection and could reverse back to his usual treatment afterwards, and one was started on repaglinide." (PMID 38331895, 2024). "Additionally, insulin priming prior to infection was found to reduce virus load in insect cell lines as well as in adult fruit flies." (PMID 39664493, 2024). "Both the immune system and insulin signaling are heavily influenced by dietary nutrition, thus any variation in the composition of diet can influence an organism’s ability to resist infection and regulate global metabolism." (PMID 37915572, 2023). "Therefore, replication of rIBVs BeauR-delGCC and BeauR-dels2m-36nt-INS were investigated in ex vivo tracheal organ cultures (TOCs), which are more representative of a natural infection." (PMID 36779761, 2023).
infection (continued). "Another possible explanation for this apparent discrepancy is that insulin resistance, leptin resistance and/or other aspects of the metabolic syndrome may perturb the infection/adipogenesis/cathelicidin pathway identified by Zhang and colleagues." (PMID 36936928, 2023). "In addition, SidC showed insulin-degrading activity, and the infection of diabetic mice resulted in higher bacterial numbers of both wt and ΔsidC bacteria compared to the infection of wt mice." (PMID 36830692, 2023). "In this study we have explored the contribution of the two Toll and Imd immune signaling pathways to regulating the survival ability, feeding rate, levels of sugar metabolites, and insulin signaling activity in D. melanogaster larvae upon infection with the parasitic nematode H. gerrardi." (PMID 37251825, 2023). "The European Society of Anaesthesiology recommends that patients drink fluids up to 2 h before surgery to mitigate risks like thirst, hunger, and metabolic changes, including reduced insulin sensitivity, which can lead to severe postoperative complications such as death and infection." (PMID 37835169, 2023). "However, when gad-transduced lymphocytes were injected into NOD mice at a high multiplicity of infection (m.o.i), insulin and blood glucose levels decreased." (PMID 37893940, 2023). "Following infection with the nematode-bacteria pairs, we assessed the changes in larval survival ability, feeding rate, and sugar levels, and also determined the transcript levels of genes involved in insulin signaling." (PMID 37251825, 2023). "However, insulin administration via continuous subcutaneous insulin infusion was reported to increase infection at the infusion site possibly due to the presence of m-cresol in such formulations." (PMID 36839885, 2023). "Notably, the infection with S. agalactiae significantly stimulated IL-1β secretion, irrespective of the glucose concentration and the presence of insulin or metformin." (PMID 36982317, 2023). "First, some factors, including laboratory indicators (such as fast plasma glucose, fasting insulin, fasting C-peptide, and C-reactive protein), site of infection, drugs, and interventions that could be related to prognosis, were not included in this study." (PMID 37608790, 2023). "The second mechanism which may be responsible for the increase in cases of T1D following SARS-CoV-2 infection is an increased demand/pressure on beta cells by a temporary increase of insulin resistance during infection." (PMID 38239343, 2023). "Several studies have revealed that infection of diet-induced obese mice with Heligmosomoides polygyrus Schistosoma mansoni and Nippostrongylus brasiliensis alleviates whole-body glucose tolerance and insulin sensitivity." (PMID 38259965, 2023). "Further RWD studies with a larger sample size and an extended follow-up period is required to verify the current study findings and to evaluate long-term safety of DPP-4 inhibitors and SGLT-2 inhibitors in terms of new-onset infections when combined with insulin in later-stage T2DM patients." (PMID 37891260, 2023). "The most common DKA triggers are insulin therapy discontinuation and infections." (PMID 37510185, 2023). "Potentially, suppression of insulin signaling could be indirectly protective against infection due to downstream effects on cap-independent translation of proteins like AMPs." (PMID 37915572, 2023). "This could be people with undiagnosed DM before getting infected with TB or those already with IGT who develop DM due to the extra insulin resistance triggered by infection." (PMID 36178364, 2022). "Furthermore, more than 43% of patients had a precipitating factor of omission of insulin, followed by infection (12%)." (PMID 36505109, 2022). "However, in the absence of a blood glucose concentration analysis, it is also difficult to see how the effect of leptin on insulin concentration affected glucose and the potential hyperglycemic state in an acute state of infection." (PMID 35897684, 2022).
infection (continued). "Therefore, microneedle platforms can deliver insulin in a way that can prevent pain and potential infection." (PMID 36290938, 2022). "Cytokines released in response to infection could have adverse effects on insulin sensitivity and pancreatic beta-cell function." (PMID 36059840, 2022). "For Leishmania, increased insulin concentrations did not result in increased vector susceptibility to infection." (PMID 35385472, 2022). "We found that infection with F. novicida inhibits insulin signalling as determined through the observance of lower levels of phosphorylated-AKT during late infection (72-80h post-injection), these flies were also hyperglycaemic and exhibited depleted triglyceride and glycogen stores." (PMID 36129961, 2022). "Lastly, LL-37 may disrupt some of the consequences of infection, such as alpha-synuclein plaque deposition in the brain, and IAPP plaque deposition in the pancreas associated with the development of insulin insensitivity." (PMID 35634307, 2022). "At the end of the experimental period, animals were humanely sacrificed using CO2 on day 0, 7, 14, 28, 35 and 42 (n = 6 in each group) post Tz-infection for collection of sera and rat carcasses for determination of serum insulin and trichinella adult worm and muscle larvae load respectively." (PMID 35923890, 2022). "We tested whether infection with F. novicida inhibits insulin signalling as has been previously reported for M. luteus infection." (PMID 36129961, 2022). "The reduction in the number of insulin secretory granules and thus impaired glucose stimulated insulin secretion during the course of infection may be attributed to this mechanism." (PMID 35215201, 2022). "Increased glucose uptake through insulin signaling pathways has been speculated to be the possible mechanism of increased glycogen accumulation post-infection." (PMID 35923890, 2022). "Infection with various helminth species or treatment with their immunomodulatory molecules have been reported to restore type 2 immunity in metabolic organs and improve insulin sensitivity and glucose homeostasis in obese mice." (PMID 35720355, 2022). "Quite the opposite, those people who were on insulin or SU therapy were at a higher risk for death than those who did not take these drugs before the infection." (PMID 36017317, 2022). "Significantly reduced insulin concentration in both Tz mono-infected and co-infected experimental groups in comparison to both the control and Pb infected groups coincided with reduced muscle glycogen concentration at day 0 days post Pb infection." (PMID 35923890, 2022). "Simultaneously, infection of obese mice with N. brasiliensis can attenuate body weight gain, decrease adipose tissue mass, and ameliorate glucose metabolism and insulin sensitivity, accompanied by a dramatic decline of insulin levels." (PMID 35281054, 2022). "We found that, following oral infection with P. entomophila, there was an increase in Akt phosphorylation in both whole-animal sample and isolated abdominal tissue samples, suggesting an increase in systemic insulin signalling." (PMID 35363274, 2022). "However, DM with insulin therapy displayed better predictive value for post-AMI infection than DM per se." (PMID 35497986, 2022). "To date, it remains unknown whether CVB-TD RNA forms are involved in the acute and chronic infection of beta cells or its impact on insulin maturation." (PMID 36560784, 2022). "To test whether this increase in insulin signalling could explain the induction of systemic TOR signalling upon infection, we examined the effects of overexpression of ImpL2, the Drosophila homolog of the mammalian insulin-like growth factor binding protein." (PMID 35363274, 2022). "Insulin therapy thus might represent the increased severity of DM to some extent, which would be more prone to develop infection." (PMID 35497986, 2022).
infection (continued). "Furthermore, because HK2 is the predominant isoform in insulin-sensitive tissues, its decreased level in the lungs further confirms the reduced insulin sensitivity in the lungs during infection in the adult mice." (PMID 35329973, 2022). "However, insulin is impacted as the ratio of secreted proinsulin to secreted insulin is higher during infection, owing to a greater secretion of proinsulin than that in mock-infected cells." (PMID 34067388, 2021). "Infection → Disruption of insulin signaling pathway and inflammation in the brain." (PMID 34795562, 2021). "Whether EV infection of the thymus could interfere with the establishment of central tolerance to insulin-secreting pancreatic β-cells has been addressed." (PMID 34072590, 2021). "Also inhibited were CEBPB and insulin-related processes, likely contributing to the reduced acute phase response (inflammatory/infection) signaling." (PMID 34209203, 2021). "This occurs on a background of inflammatory responses to trauma or infection, increased circulating cytokine, glucagon, epinephrine, and glucocorticoid treatment, hyperglycemia-mediated secondary infections, and induction of muscle insulin resistance." (PMID 34769017, 2021). "The roles of insulin and leptin in central nervous system (CNS) infection." (PMID 34795562, 2021). "Moreover, increasing insulin signalling in the FB leads to decreased immune gene expression and, vice versa, decreasing insulin signalling leads to increased immune gene expression and increased resistance to infection (Musselman and Kühnlein, 2018)." (PMID 34993199, 2021). "This approach opens up prospects for studying the cellular consequences of infection; however, other strategies retain their interest, since the disturbances in insulin metabolism (Insulin/proinsulin ratio and PCSK2 inhibition) in the present study were demonstrated by ELISA and real-time RT-PCR." (PMID 34067388, 2021). "In conclusion, these findings shed new light on the thymic IGF2 regulation by CV-B4 infection, thus strengthening the hypothesis of a possible role of CV-B infections in decreasing central tolerance to insulin." (PMID 33672010, 2021). "Furthermore, in an EcoHIV mouse model intranasal insulin beginning 23 days or 3 months post infection reversed neurocognitive impairments in mice." (PMID 32650790, 2020). "This requires collecting and analyzing infection-related data, and estimating the overall changes each pathogen could bring on insulin sensitivity during the course of infection." (PMID 32784178, 2020). "To determine if the decrease in insulin secretion was in part a consequence of virus-induced SC-β cell death, we measured cell viability at 48 and 72 h post-infection using annexin V and 7-amino-actinomycin D (7-AAD) staining and flow cytometry to measure apoptosis and necrosis, respectively." (PMID 32093375, 2020). "One possible approach could be characterizing the effect of different pathogens on blood glucose dynamics, mainly on insulin resistance and its sensitivity change over the course of infection." (PMID 32784178, 2020). "The patient can only estimate the disturbance caused by the amount of carbohydrate consumption, insulin injection, and physical activity load, which is not the case during infection incidence." (PMID 32784178, 2020). "Considering its vital roles in both stress resistance and lifespan determination, we hypothesized that the insulin signaling pathway plays an important role in protecting older worms from infection." (PMID 32161087, 2020). "Furthermore, we demonstrated a significant up-regulation of the Def C expression and a decrease of the viral RNA replication in the insulin-fed midguts by 1 day post infection (d.p.i), compared to the PBS-fed controls." (PMID 32866199, 2020). "Also, an often-noted clinical observation in subjects with T1D is the temporary increase in needs of exogenous insulin during infections, which is attributed to increased insulin resistance." (PMID 31520124, 2020).